GPR176 (G protein-coupled receptor 176)
Description:
Orphan receptor involved in normal circadian rhythm behavior. Acts through the G protein subclass G(z)-alpha and has an agonist-independent basal activity to repress cAMP production.
Synonyms: Gm1012; HB-954
Tractability: Small molecule: it belongs to a druggable protein family. Antibody: its Gene Ontology location is reachable by antibodies, with high confidence; UniProt places it where antibodies can reach, with medium confidence; UniProt predicts a signal peptide or a membrane-spanning region.
Target class: Family A G protein-coupled receptor; Membrane receptor
Gene: Protein-coding gene on chromosome 15 (39,799,008 to 39,920,936, reverse strand). Ensembl gene ENSG00000166073.
Subcellular location: Cell membrane
Pathways (Reactome):
Signal Transduction: G alpha (s) signalling events
Gene Ontology:
Molecular function: G protein-coupled receptor activity
Biological process: adenylate cyclase-inhibiting G protein-coupled receptor signaling pathway; chemical synaptic transmission; circadian behavior; G protein-coupled receptor signaling pathway; cell communication; signaling
Cellular component: plasma membrane; membrane; synapse
Genetic constraint (gnomAD): Loss-of-function variants: 21 observed, 28.64 expected, observed/expected ratio (o/e) 0.73, 90% interval 0.52 to 1.06. The upper end of that interval is the gene's LOEUF score, 1.06, which puts it in group 4 of 6, group 1 being the genes least tolerant of losing a copy. Missense variants: 589 observed, 653.74 expected, observed/expected ratio (o/e) 0.9, 90% interval 0.84 to 0.96. Synonymous variants: 273 observed, 266.1 expected, observed/expected ratio (o/e) 1.03, 90% interval 0.93 to 1.13.
Homologues: Orthologues: chimpanzee GPR176 (99% identical), macaque GPR176 (99% identical), dog GPR176 (93% identical), mouse Gpr176 (90% identical), rat Gpr176 (90% identical), guinea pig GPR176 (90% identical), rabbit GPR176 (90% identical), pig GPR176 (83% identical), tropical clawed frog gpr176 (73% identical), zebrafish gpr176 (63% identical). Paralogues in human: GPR135 (17% identical), GPR61 (15% identical), GPR62 (12% identical).
Diseases named in the same sentence as GPR176 in open-access papers:
GPR176 is named in the same sentence as 30 diseases in open-access papers, as found by Europe PMC text mining. Sharing a sentence is not in itself a finding about the gene and the disease. The quoted sentences say what the papers report.
colorectal cancer (6 papers, 2023 to 2025). A primary or metastatic malignant neoplasm that affects the colon or rectum. "GPR176 facilitates colorectal cancer progression through its interaction with GNAS, leading to the inhibition of mitophagy." (PMID 40316942, 2025). "In the present study, expression analyses of GPR176 are performed in patients with colorectal cancer." (PMID 36905238, 2023). "GPR176 promotes colorectal carcinoma progression by interacting with the G protein GNAS." (PMID 40689396, 2025). "GPR176 belongs to the G protein‐coupled receptor superfamily, which responds to external stimuli and regulates cancer progression, but its role in colorectal cancer (CRC) remains unclear." (PMID 36905238, 2023). "G protein-coupled receptor 176 (GPR176) regulates mitophagy via the cAMP/PKA/BNIP3L axis, leading to initiation and progression of colorectal cancer." (PMID 39035027, 2024). "GPR176 has been found to activate the cAMP/PKA pathway in colorectal cancer, and its transmembrane helix 3-intracellular loop 2 domain has been observed to recruit GNAS, thereby amplifying the intracellular GPR176 signal." (PMID 37584712, 2023).
breast carcinoma (4 papers, 2020 to 2023). "Moreover, GPR176 mRNA hypoexpression was closely linked to promoter hypermethylation in breast cancer, indicating that GPR176 methylation is responsible for its downregulated mRNA expression." (PMID 37079213, 2023). "Lower expression of GPR176 mRNA was seen in breast cancer than in normal tissues, but the opposite pattern was found for its protein (p < 0.05)." (PMID 37079213, 2023). "GPR176 methylation was negatively correlated with its mRNA level and T staging in breast cancer, and was higher in breast cancer than normal tissues (p < 0.05)." (PMID 37079213, 2023). "In breast cancer cells, the expression of GPR176 mRNA was noted to be inversely related to purity, but positively linked to the presence of immune cell infiltration." (PMID 37079213, 2023). "In breast cancer cells, GPR176 silencing was shown to ameliorate proliferation and induce apoptosis by either inactivating PTEN/PI3K/Akt/mTOR or decreasing Bcl-2/Bax." (PMID 37079213, 2023). "According to a densitometric analysis of the western blot, GPR176 expression was higher in breast cancer than in matched normal tissues (p < 0.05)." (PMID 37079213, 2023). "Here, GPR176 silencing was found to suppress the proliferation, anti-apoptosis, migration and invasion of breast cancer cells." (PMID 37079213, 2023). "Gpr176 encodes a class-A orphan GPCR that has a role in circadian clock regulation in mouse hypothalamus and is also implicated in human breast cancer transcriptional response." (PMID 32157140, 2020). "GPR176 expression was detected by qRT-PCR, bioinformatics analysis, Western blot and immunohistochemistry, and compared with clinicopathological characteristics of breast cancer." (PMID 37079213, 2023). "Taking the obtained findings together, GPR176 might act as a biological marker to indicate the development of breast cancer." (PMID 37079213, 2023). "GPR176 immunoreactivity was significantly lower in normal breast than in breast cancer (p < 0.05)." (PMID 37079213, 2023). "This discrepancy might be due to the rapid translation of GPR176 mRNA and high stability of GPR176 protein in breast cancer." (PMID 37079213, 2023). "During the progression of breast cancer, GPR176 expression might be regulated by other factors as a negative feedback regulation." (PMID 37079213, 2023). "In summary, GPR176 is believed to be involved in the pathogenesis and subsequent progression of breast cancer by promoting the proliferation, anti-apoptosis, glucose catabolism, migration, and invasion of breast cancer cells." (PMID 37079213, 2023). "GPR176 mRNA expression was also negatively correlated to the T staging of breast cancer (p < 0.05)." (PMID 37079213, 2023). "Our study found that the expression of GPR176 protein was associated with an older age, a smaller tumor size and the non-luminal B subtype of breast cancer." (PMID 37584712, 2023). "Here, we found that GPR176 was downregulated in breast cancer by both real-time PCR and bioinformatics analysis, but upregulated by both western blot and immunohistochemistry, indicating that aberrant GPR176 expression plays an important role in breast carcinogenesis." (PMID 37079213, 2023). "We also explored the effects of GPR176 on the phenotypes of breast cancer cells." (PMID 37079213, 2023). "GPR176 knockdown weakened the proliferation, glucose catabolism, anti-apoptosis, anti-pyroptosis, migration, invasion, and epithelial-mesenchymal transition of breast cancer cells." (PMID 37079213, 2023). "Taken together, we speculated that GPR176 might promote breast carcinogenesis by deteriorating the aggressive phenotypes of breast cancer cells." (PMID 37079213, 2023).
breast carcinoma (continued). "Additionally, upregulated GPR176 protein expression in breast carcinogenesis was downregulated with the progression of breast cancer, suggesting that GPR176 protein might be involved in breast carcinogenesis as an early event." (PMID 37079213, 2023). "In addition, GPR176 expression was associated with older age, smaller tumor size, and the non-luminal-B subtype of breast cancer (p < 0.05)." (PMID 37079213, 2023). "Moreover, the protein expression of GPR176 was significantly increased in breast cancer and it may serve as a potential biomarker to indicate poor prognosis of breast cancer as well as a potential target for gene therapy." (PMID 37291181, 2023). "In ovarian cancer, we found that GPR176 mRNA expression positively correlated with older age, clinicopathological staging and tumor residual status, while GPR176 expression at both mRNA and protein levels was associated with low T staging and good PAM50 classification of breast cancer." (PMID 37584712, 2023). "Moreover, GPR176 knockdown has been found to impede the proliferation, glucose catabolism, anti-apoptotic and anti-pyroptotic properties, migration, invasion and epithelial-mesenchymal transition of breast cancer cells, which is in agreement with results obtained from ovarian cancer cells." (PMID 37584712, 2023). "There was a negative relationship between GPR176 mRNA expression and promoter methylation in breast cancer, according to the cBioPortal database (p < 0.05)." (PMID 37079213, 2023). "GPR176 silencing was shown to reduce the expression of MMP1, MMP9, and VEGF, accounting for the effects of GPR176 in promoting the invasion and metastasis of breast cancer cells." (PMID 37079213, 2023). "Therefore, we believed that GPR176 knockdown promoted pyroptosis and suppressed the EMT of breast cancer by increasing the levels of Zeb1, Slug, Snail, and Twist1." (PMID 37079213, 2023). "GPR176 protein expression was positively correlated with older age, small tumor size, and non-luminal-B subtype of breast cancers (p < 0.05)." (PMID 37079213, 2023). "GPR176 promoter methylation was higher in breast cancer than in normal tissues,in Caucasians than in African-Americans according to UALCAN (p < 0.05)." (PMID 37079213, 2023). "In addition, we found that GPR176 knockdown might inhibit migration, invasion, and glycolysis and mitochondrial oxidation of glucose in breast cancer cells, indicating that GPR176 might exacerbate the aggressive phenotypes of breast cancer cells, including invasion and glucose consumption." (PMID 37079213, 2023). "Additionally, GPR176 knockdown was observed to reduce the proliferation, glucose catabolism, anti-apoptotic and anti-pyroptotic properties, migration, invasion and epithelial-mesenchymal transition (EMT) of breast cancer cells." (PMID 37584712, 2023).
esophageal cancer (4 papers, 2023 to 2026). A primary or metastatic malignant neoplasm involving the esophagus. "GPR176 mRNA expression was associated with low weight and BMI, low T stage, low N and clinicopathological stage, low histological grade and favourable clinical outcome of oesophageal cancer (p < 0.05)." (PMID 37584712, 2023). "Bioinformatics and clinical tissue samples were used to detect the expression and clinicopathological significance of GPR176 in oesophageal cancer." (PMID 37584712, 2023). "In oesophageal cancer cells, GPR176 silencing was shown to ameliorate proliferation and induce apoptosis by either inactivating PI3K/Akt/mTOR or decreasing Bcl-2/Bax." (PMID 37584712, 2023). "Here, RT-PCR and bioinformatic analyses revealed that GPR176 mRNA expression was significantly higher in oesophageal cancer than in normal mucosa (p < 0.05)." (PMID 37584712, 2023). "The expression, proliferation, migration and invasion, apoptosis and lipid droplet formation of GPR176 gene in oesophageal cancer were performed as phenotypic readouts." (PMID 37584712, 2023). "GPR176 expression was gradually increased from distal to proximal sites of oesophageal cancer (p < 0.05)." (PMID 37584712, 2023). "In line with the findings on gastric cancer, we found that GPR176 mRNA expression was upregulated in oesophageal cancer, and positively correlated with T and N clinicopathological staging, and dedifferentiation of oesophageal cancers." (PMID 37584712, 2023). "In summary, GPR176 is believed to be involved in the pathogenesis and subsequent progression of oesophageal cancer by promoting proliferation, anti-apoptotic and anti-pyroptotic properties, migration, invasion and EMT of oesophageal cancer cells." (PMID 37584712, 2023). "The rates of positivity for GPR176 expression were 76.9% (226/294) and 79.4% (259/326) in oesophageal normal mucosa and oesophageal cancer, respectively." (PMID 37584712, 2023). "The current study was performed to evaluate the impact of GPR176 on the clinicopathology and prognosis of oesophageal cancer, as well as uncover its molecular mechanisms." (PMID 37584712, 2023). "This suggests that GPR176 is involved in the differentiation of oesophageal cancer at both mRNA and protein levels." (PMID 37584712, 2023). "Against this background, the current study was performed to evaluate the impact of GPR176 on the clinicopathology and prognosis of oesophageal cancer, as well as uncover its molecular mechanisms." (PMID 37584712, 2023). "We hypothesised that GPR176 could be a factor contributing to the development and progression of oesophageal cancer, as it appears to worsen the aggressiveness of gastric cancer cells." (PMID 37584712, 2023). "Taking these findings together, we hypothesise that GPR176 might strengthen the aggressiveness of oesophageal cancer cells by affecting cell adhesion and mobility, membrane and lipid rafts." (PMID 37584712, 2023). "This indicated that GPR176 mRNA overexpression might be involved in the carcinogenesis and subsequent progression of oesophageal cancer." (PMID 37584712, 2023). "Taking these findings together, GPR176 might be available as a biological marker to predict the outcome of oesophageal cancer patients." (PMID 37584712, 2023). "The top GPR176-correlated genes (PDPH, KIREL1, CLEC12A-AS1, CERCAM, IKBIP, LOX, COL5A2 and ELF3) were more highly expressed in oesophageal cancer than in normal tissue (p < 0.05), but the converse was true for C9orf152 and MT-TP (p < 0.05)." (PMID 37584712, 2023). "GPR176 protein was not correlated with the prognosis of oesophageal cancer patients, but sex, T staging, N staging and TNM staging were shown to be prognostic risk factors." (PMID 37584712, 2023). "First, we performed real-time RT-PCR and found that GPR176 mRNA expression was higher in oesophageal cancer than in normal tissue (p < 0.05), in line with the data from both xiantao (p < 0.05) and UALCAN datasets (p < 0.05)." (PMID 37584712, 2023).
esophageal cancer (continued). "GPR176 might induce chemoresistance by ACC1- and ACLY-mediated lipogenesis and lipid droplet assembly in oesophageal cancer cells." (PMID 37584712, 2023). "Through our research, we determined that GPR176 knockdown could stimulate pyroptosis and inhibit the EMT of oesophageal cancer by reducing the levels of Slug and Snail." (PMID 37584712, 2023).
gastric adenocarcinoma (4 papers, 2023 to 2024). "Moreover, both CTLA4- and PD-1 positive and negative gastric adenocarcinomas with low expression of GPR176 had better responses to ICIs." (PMID 39711962, 2024).
gastric cancer (3 papers, 2023 to 2025). A primary or metastatic malignant neoplasm involving the stomach. "We aim to investigate the diagnostic and prognostic value of GPR176 in gastric cancer (GC) and explore its potential mechanism." (PMID 37291181, 2023). "In this regard, it was shown that GPR176 silencing reduced the expression of MMP9, which explained GPR176’s effects of promoting the invasion and metastasis of gastric cancer cells." (PMID 37584712, 2023).
ovarian carcinoma (2 papers, 2023). A malignant neoplasm originating from the surface ovarian epithelium. "Studies on ovarian cancer have demonstrated that GPR176 mRNA was associated with lower overall, progression-free and post-progression survival rates, regardless of the stratification of clinical parameters." (PMID 37584712, 2023). "In addition, GPR176 was identified as a cancer-associated fibroblast marker specific to ovarian cancer and could help guide the prognostic assessment of ovarian cancer." (PMID 37291181, 2023).
Anxiety (1 paper, 2025). Intense feelings of nervousness, tension, or panic often arise in response to interpersonal stresses. "The increased activity of PV + interneurons after the knockdown of Gpr176 suggests enhanced inhibitory activity in the orbitofrontal cortex of affected mice, and affected mice showed lower levels of anxiety-like behavior." (PMID 41188983, 2025). "Furthermore, the knockdown of Gpr176 in PV + interneurons of the prefrontal cortex led to decreased anxiety-like behavior in mice." (PMID 41188983, 2025). "Indeed, in the present study, we found knockdown of Gpr176 led to decreased anxiety of mice in the OFT test." (PMID 41188983, 2025). "Knockdown Gpr176 of PV + interneurons and inhibited their activities at the same time did not restore the anxiety level, which further suggests that Gpr176 in PV + interneurons is critical to brain functions." (PMID 41188983, 2025).
atherosclerosis (1 paper, 2016). A disease characterized by the build-up of fatty material and calcium deposition in the arterial wall resulting in partial or complete occlusion of the arterial lumen. "Amongst these differentially expressed genes, we noted a positive association between BMPR1A-biased BMP2 expression and GPR176, an orphan G-protein coupled receptor thought to be involved in atherosclerosis." (PMID 27114889, 2016).
Cognitive impairment (1 paper, 2024). Abnormal cognition is characterized by deficits in thinking, reasoning, or remembering. "Genes involved in the cognitive impairment MAG, GDF15, GPR176, and EPHB1 (upregulated), BCL11B, GIMAP7, and ACOD1 (downregulated) were differentially expressed." (PMID 38755198, 2024).
oesophageal adenocarcinoma (1 paper, 2023). "As for oesophageal adenocarcinoma, GPR176 mRNA expression was negatively related to the OS of all and male cancer patients, and those at Grade 2 and with a high mutation burden (p < 0.05)." (PMID 37584712, 2023).
triple-negative breast carcinoma (1 paper, 2023). An invasive breast carcinoma which is negative for expression of estrogen receptor (ER), progesterone receptor (PR), and human epidermal growth factor receptor 2 (HER2).